IL6 (interleukin 6)
Diseases named in the same sentence as IL6 in open-access papers (continued):
Sharing a sentence is not in itself a finding about the gene and the disease.
infection (continued). "The presumed mechanism for this association suggests that infection downregulates CYP 1A2 by about 90% through increase in circulating IL-6, interferon, and TNF-α." (PMID 22934219, 2012). "The direct cellular effect of histamine and its ability to synergize LPS-induced IL-6 production underscores its role in amplifying the inflammatory responses associated with infection." (PMID 22363102, 2012). "Differences between the central and peripheral pattern of IL-6 were associated with episodes of ventriculostomy-related infection (VRI)." (PMID 23176037, 2012). "Genes associated with JAK-STAT3-mediated IL-6 signalling were upregulated early and throughout infection." (PMID 22679491, 2012). "TNF-α is one of the first cytokines to be released by macrophages in response to infection and, once in the circulation, it causes systemic inflammation through stimulating the widespread release of downstream cytokines, such as interleukin-6 (IL-6) and IL-8." (PMID 22340283, 2012). "The levels of CXCL1, CXCL10, CCL1, CCL3, IFN-γ, TNF-α and IL-6 were significantly increased in the lungs of RSV-infected IL-10-deficient mice compared to control mice on day 8 post infection." (PMID 22393401, 2012). "Elevated levels of IL-6 were associated with severe disease in patients hospitalized with H1N1pdm infection." (PMID 22679491, 2012). "Recently, increased IL-6 expression was observed in severe cases of H1N1pdm infection, with a significant inverse association between IL-6 and arterial oxygen levels in patients hospitalized with H1N1pdm infection." (PMID 22679491, 2012). "IL-6 appears to be among the most sensitive and specific indicators of infection-associated preterm labour." (PMID 22719180, 2012). "Taken together, these results revealed a strong association of IL-6 patient concentration to disease severity in people hospitalized with H1N1pdm infection." (PMID 22679491, 2012). "Increased IL-6 expression in both patients hospitalized with H1N1pdm and mouse models of H1N1pdm implicated IL-6 in the host response to infection." (PMID 22679491, 2012). "Among humans hospitalized with H1N1pdm infection, we found serum IL-6 levels associated strongly with requirement of critical care admission and fatal outcome." (PMID 22679491, 2012). "IL-6-deficient mice that survived infection became long-term carriers despite the presence of abundant IFN-γ-producing 2W:I-Ab-specific CD4+ T cells." (PMID 21966268, 2011). "In contrast, infection with the human apathogenic TCRV was associated with high levels of IL-6, IL-10 and TNF-α." (PMID 21572983, 2011). "On the other hand, IL-6−/− mice were more susceptible to PTV infection and supported higher levels of viremia than did wt mice, which possibly means that IL-6 is indispensable for protective immunity." (PMID 21666766, 2011). "Elevated IL-6 concentrations have been associated with infection and inflammation in a variety of disease conditions." (PMID 19698101, 2009). "IL-6 deficient mice were unable to control infection by vaccinia virus and lymphocytic choriomeningitis virus (LCMV)." (PMID 19587788, 2009). "Using an enzyme-linked immunosorbent assay (ELISA), we found that IL-6 levels were increased in the lungs of P58IPK−/− mice compared with wild-type animals throughout the course of infection." (PMID 19461876, 2009). "Functions most strongly associated with virulent strain infection included cytokine–cytokine receptor interactions and a number of immune signaling pathways, such as interleukin (IL)-6, IL-10 and nuclear factor κB." (PMID 19845042, 2009). "The rapid activation of tissue macrophages early in the innate immune response to infection causes the release of cytokines interleukin-6 (IL-6), interleukin-1β (IL-1β), and tumor necrosis factor-α (TNF-α), along with other proinflammatory mediators." (PMID 18242584, 2008).
infection (continued). "On the fifth postoperative day, CRP greater than 12 mg/l (OR = 25.92; 95% CI: 2.17-332.71; p < 0.01) and IL-6 greater than 25 pg/ml (OR = 15.46; 95% CI: 1.19-230.30; p = 0.03) were the only variables associated with infection." (PMID 17505683, 2007). "On the second postoperative day, CRP greater than 30 mg/l (OR = 8.27; 95% CI: 1.05-64.79; p = 0.03) in association with infection and IL-6 higher than 50 pg/ml was marginally significant (OR = 8.31; 95% CI: 0.81-84.50; p = 0.07)." (PMID 17505683, 2007). "Our study data suggest that LBP (cut off level 20 μg/ml), CRP (cut off level 30 mg/l) and IL-6 (cut off level 16.3 pg/ml) are comparable in terms of their diagnostic abilities in diagnosing infection." (PMID 16569262, 2006). "Severity-of-illness indices (SAPS-II and MCCI) and inflammation-based biomarkers (NLR, PLR, CRP, and IL-6) were closely linked to both the timing of infection onset and in-hospital mortality, highlighting their potential value for early risk stratification in critically ill patients." (PMID 41597404, 2026). "Furthermore, exaggerated IL‐6 release in human BECs results from innate immune training by repetitive infection with RV16 (or poly(I:C)), that is, in turn, associated with IL6TS high expression and a low IL6 gene methylation profile." (PMID 41099307, 2026). "Like IL-6 inhibitors, the systemic immunosuppressive nature of infliximab may increase susceptibility to infections." (PMID 41530118, 2026). "Finally, we found that lasR LOF mutations altered the inflammatory profile upon infection of CF macrophages, with a shift from IL-1 family cytokine expression toward canonical inflammatory markers, including IL-6 and TNFα." (PMID 41925330, 2026). "In perinatal inflammatory conditions, IL-17-associated inflammatory programs have been increasingly implicated in infection and intrauterine inflammation, and can converge on the induction of inflammatory mediators such as interleukin-6 (IL-6) and cyclooxygenase-2 (COX-2)." (PMID 41598260, 2026). "In our study, IL-6 levels were significantly elevated in infected patients starting from day 3 postoperatively, making it a useful marker for identifying patients at risk of infection-related complications." (PMID 40806991, 2025). "Additionally, both viral strains induce elevated IL-6 secretion at 7 and 10 days post-infection; although IL-6 is commonly associated with inflammation, it also plays a role in metabolic regulation and can promote adipocyte browning under specific conditions." (PMID 40746960, 2025). "Using Nlrx1−/− mice, IAV infection resulted in a significant increase in IFN signaling and the production of IFN‐β compared to wild‐type mice, leaving Nlrx1−/− more susceptible to infection by increasing airway epithelial cell denuding, obscured small airways, and IL‐6 production." (PMID 39878363, 2025). "We showed a significant induction of immune response (significant upregulation of TNF-α and IL-6) by PHGFs infected with each P. gingivalis strain harbouring the G231N, E232T, N235D variant in comparison with expression of both genes due to infection with wt-P." (PMID 40004125, 2025). "Interleukin (IL)-6 is usually produced after infection, and elevated IL-6 levels may cause multisystemic damage." (PMID 40136690, 2025). "In the multivariable analysis, after adjusting for age, severity of TBI, and the presence of hospital infection, admission IL-6 remained significantly associated with the probability of an adverse outcome at 6 months with a sensitivity of 75% and a specificity of 89% for a cut-off point of 59 pg/ml." (PMID 40713822, 2025). "The table below presents the mean values of the concentrations of the analyzed proinflammatory cytokines; TNF-α, IL-1β and IL-6 (expressed in picograms per milliliter [pg/mL]) ± standard deviation measured in patients with PCOS with infections caused by atypical pathogens and in the control groups." (PMID 40647668, 2025).
infection (continued). "While mechanical trauma or infection is often suspected, the true trigger may lie in immune predisposition, reflected by elevated systemic interleukin-6 (IL-6), IL-17, or high-sensitivity C-reactive protein." (PMID 41394265, 2025). "A major limitation regarding the use of IL-6 as a standard diagnostic tool for PJI was identified in the case of low-grade infections, especially in shoulder infections known to be caused by less virulent bacteria, in which case the sensitivity of the test was as low as 0.13–0.14." (PMID 40981112, 2025). "In addition to cell death, LF82 infection resulted in secretion of proinflammatory cytokines IL-1β, IL-6, IL-8, and TNF-α, indicating a causative or at least exacerbating role of AIEC in CD." (PMID 41163391, 2025). "A low FT3 state has been linked to impaired immune cell function, resulting in increased production of pro-inflammatory cytokines such as TNF-α and IL-6, which can exacerbate systemic inflammation, compromise pulmonary defense barriers, and heighten susceptibility to infection." (PMID 41296678, 2025). "In the mouse infection model, Ply5218 repeated dosing (6, 24, and 48 h post-infection) not only alleviated the clinical symptoms caused by Streptococcus in piglets, but also significantly reduced the bacterial loads and the level of interleukin-6 (IL-6)." (PMID 40071209, 2025). "In the inflammatory response caused by infection, the brain’s response to body temperature originates from the stimulation of the thermoregulatory center by chemicals such as endogenous (like bacterial endotoxin) and exogenous pyrogens (like interleukin-6)." (PMID 40005342, 2025). "Moreover, pulmonary IL-6 level upon infection significantly decreased in mice deficient in caspase-11 or NLRP3." (PMID 40034692, 2025). "IL-6 can cause gut inflammation, but it can also help the body fight infections." (PMID 39857830, 2025). "Despite the lack of microglia or other immune cells in this system, the levels of several proinflammatory cytokines were increased upon infection by all three EVs, including cytokines previously associated with EV neuropathogenesis such as IL-6, IL-8 and CCL5 (RANTES)." (PMID 41332624, 2025). "Furthermore, montelukast treatment substantially decreased serum levels of TNF-α and IL-6 following infection, thereby ameliorating infection-associated organ dysfunction caused by excessive inflammation." (PMID 41090944, 2025). "IL-6 is a cytokine involved in inflammatory reactions, and the IL-6 inhibitory effect of satralizumab suppresses fever symptoms and increase in blood level of C-reactive protein, which poses a risk of delaying the detection of infection." (PMID 39470886, 2025). "Elevated levels of IL-6 are commonly associated with acute immune responses and infection control." (PMID 39858197, 2025). "Future multicenter, prospective studies incorporating microbiological adjudication, adjustment for clinical confounders, and expanded biomarker panels (e.g., procalcitonin and IL-6) are required to clarify mechanisms and establish reliable infection risk models after PCI." (PMID 41008500, 2025). "Elderly patients have blunted and easily dysregulated host responses to infection, which may influence IL-6 kinetics and alter the association between IL-6 levels and clinical outcomes." (PMID 39800741, 2025). "Interleukin (IL)-6 is associated with wound healing and infection response." (PMID 40098608, 2025). "Elevated CRP, IL-6, and procalcitonin levels may signal the need for enhanced postoperative monitoring and infection risk management." (PMID 39857688, 2025). "For instance, active transcription is linked to the methylation of histone H3 on lysine 4 (H3K4me3), and its presence at loci encoding pro-inflammatory molecules like TNF-α and IL-6 and cytokine gene loci like those encoding IFNs can increase their expression during infection." (PMID 40969755, 2025).
infection (continued). "To explore whether IL-6 is causal in infection, or simply correlated with disease, we used Mendelian randomisation." (PMID 40819633, 2025). "Siltuximab blocks IL-6 signaling, which might interfere with acute-phase response to pathogens and increase the risk of infection." (PMID 41220922, 2025). "The authors concluded that elevated pre-intervention levels of serum TNF-α and IL-6 may indicate a predisposition to post-intervention inflammation and infections following URS treatment." (PMID 38327930, 2024). "Moreover, synthesis of IL‐6 is associated with infection defence, improved lipid metabolism, and glucose metabolism." (PMID 39632267, 2024). "Although IL-6, procalcitonin, and C-reactive protein are commonly utilized biomarkers for assessing infection and hypothesizing potential causes, they primarily reflect inflammation levels and exhibit limited utility in early detection and predicting outcomes." (PMID 39744123, 2024). "The increase in IL-6 may be due to a) autoantibodies, b) germline mutations in genes regulating inflammation, c) oncogenic mutations, and d) infection with pathogens." (PMID 39100061, 2024). "The infection and corresponding tissue damage caused by DD elicit the host to produce elevated levels of pro-inflammatory cytokines, such as interleukin-1β (IL-1β) and interleukin-6 (IL-6), released into the blood stream." (PMID 39595313, 2024). "Finally, regarding patients in Ph II with primary infection, only a significant association was observed for IL-6 and white blood cells." (PMID 39457019, 2024). "Our research shows that infection of rabbits with L. europaeus/GI.1 and GI.2 genotypes causes an increase in the expression of two critical acute phase cytokines—IL-6 in all examined tissues (liver, lungs, kidneys, and spleen) and TNF-α (in the liver, lungs, and spleen)." (PMID 39273479, 2024). "We noted that the significantly activated IL-6-encoded gene persisted at 4 weeks after infection." (PMID 39475775, 2024). "In the large intestine, infection with the Alpha strain strongly correlated with IL-2, and Beta and Delta infections were highly associated with multiple inflammatory cytokines (IL-1β, IL-6, IL-8, IL-18, TGF-α and MIP-1α)." (PMID 38563680, 2024). "Notably, infection-associated MHCII downregulation has also been partly attributed to IL-6 signaling in other models." (PMID 37982695, 2024). "An IL-6 concentration < 10 pg/ml might be associated with increased infection risk (AOR = 1.69, 95%CI = 0.97–2.94)." (PMID 38616284, 2024). "In healthy individuals, SAA levels are low; however, infection by bacteria or viruses causes cytokines such as interleukin-1, interleukin-6, and tumor necrosis factor to prompt the liver to secrete SAA, leading to a significant increase in its levels within 8 to 12 h." (PMID 39039452, 2024). "In a meta-analysis study of the literature, a significant increase in circulating levels of IL-6 and TNF-a was found during infection with the bacteria, when it was also associated with GC, increased serum levels of IL-6 IL-7, IL-10, IL-12 and TNF-a were found." (PMID 38455038, 2024). "Moreover, the imbalance between IL-6 agonistic and antagonistic molecules suggests a dynamic modulation of IL-6 levels associated with the severity of infection." (PMID 39063569, 2024). "Of note, the infection caused significant upregulation in mRNA expression level of interferon-stimulated genes (Isg15, Mx1, Mx2, Irf3, and Irf7) and pro-inflammatory cytokines (Tnf-α, Cxcl-1, and Il-6 genes)." (PMID 37929187, 2023). "It is unknown whether the association between HDL and infection is present for all particle sizes, and whether the observed associations are confounded by IL-6 signalling." (PMID 37814277, 2023). "However, the presence of pro-inflammatory cytokines, such as IL-6, is related to a higher risk of complications from this infection." (PMID 36897879, 2023).
infection (continued). "IL-6 is a cytokine produced by a variety of cells, including monocytes and macrophages, in response to immune responses, and can be significantly upregulated in pathogenic infection." (PMID 37402969, 2023). "In pregnant women with SARS-CoV-2 infection, raised IL-6 concentrations have been correlated with the severity of infection and IL-6 is one of several cytokines linked with preterm labour associated with maternal infection, and as already discussed, is probably capable of crossing the placenta." (PMID 37332846, 2023). "Despite cut-off limits for this marker not being definitively established, the serial measurement of IL-6 or combinations with other specific biomarkers of infection could improve the diagnostic potential of IL-6." (PMID 37627653, 2023). "The IL-6 level is probably the single most important factor associated with the hepatic acute-phase response and this is a response to tissue damage or infection that initiates host defense mechanisms and whose goal is to eliminate the threat and facilitate tissue repair." (PMID 36200436, 2023). "Early study of the proinflammatory response to Chlamydia also indicated that infection also induces production of fibrosis-associated cytokines such as IL-6, IL-11, and IL-17, as well as an extensive portfolio of fibrosis-associated growth factors (e.g. VEGF, CTGF, EGF)." (PMID 37265500, 2023). "Taken together with the association between infection status and IL-6 levels, these suggest that inflammation processes continue with persistent infections as older children may have been exposed to infections for longer." (PMID 37018184, 2023). "IL-6 is associated with the cytokine storm that occurs in severe infections." (PMID 37005767, 2023). "However, the presence of pro-inflammatory cytokines, such as IL-6, is associated with an increased risk of complications from this infection." (PMID 36897879, 2023). "Other studies have shown that, in anosmia, the loss of olfactory function could be correlated with infection of the olfactory epithelium and increased expression of cytokines such as IL-6." (PMID 37261613, 2023). "Therefore, the association with infection is unclear given that both IL-6 and CRP are rapidly restored to the normal range once the infection is cleared." (PMID 37789021, 2023). "While IL-6 is predominantly associated with disease severity in TB, knockout studies have shown that IL-6 plays an important role in controlling bacterial load early in the infection through induction of protective interferon gamma-producing T cell responses." (PMID 37653422, 2023). "IL-6 is associated with chronic inflammation, and has been suggested as a biomarker of infection." (PMID 37614559, 2023). "A reduction in the proinflammatory cytokines IL-1β, IL-6, and IL-8 produced by Th1 cells may increase the risk of infection and virus reactivation." (PMID 36904156, 2023). "Interleukin 6 is also a suggestive marker being involved in the infection-associated inflammatory response; it is a “stress cytokine” whose concentration increases in patients affected by suppurations or in those undergoing surgery; it is a marker that can guide therapeutic decisions." (PMID 36836892, 2023). "Moreover, the levels of pro-inflammatory cytokines IFN-γ, TNF-α, IL-1β, and IL-6 were significantly lower in the Δα-amy group, further suggesting that infection with Δα-amy cysts hardly caused remarkable inflammatory damage to intestinal tissues." (PMID 38087373, 2023). "Common biomarkers, such as C-reactive protein (CRP), procalcitonin (PCT), and interleukin-6 (IL-6), are generally associated with inflammation, and thus, their specificity for infection is low and could be affected by many other reasons." (PMID 37181361, 2023). "Patients with GCA are often old and could have multiple comorbidities combined with increased susceptibility to infection, which may hamper the enthusiasm of using IL-6-blocking therapy." (PMID 37304255, 2023).